IGHV4-59 (immunoglobulin heavy variable 4-59)
Description:
V region of the variable domain of immunoglobulin heavy chains that participates in the antigen recognition. Immunoglobulins, also known as antibodies, are membrane-bound or secreted glycoproteins produced by B lymphocytes. In the recognition phase of humoral immunity, the membrane-bound immunoglobulins serve as receptors which, upon binding of a specific antigen, trigger the clonal expansion and differentiation of B lymphocytes into immunoglobulins-secreting plasma cells. Secreted immunoglobulins mediate the effector phase of humoral immunity, which results in the elimination of bound antigens. The antigen binding site is formed by the variable domain of one heavy chain, together with that of its associated light chain. Thus, each immunoglobulin has two antigen binding sites with remarkable affinity for a particular antigen. The variable domains are assembled by a process called V-(D)-J rearrangement and can then be subjected to somatic hypermutations which, after exposure to antigen and selection, allow affinity maturation for a particular antigen.
Synonyms: IGHV459; VH
Tractability: Antibody: its Gene Ontology location is reachable by antibodies, with high confidence; UniProt places it where antibodies can reach, with medium confidence; UniProt predicts a signal peptide or a membrane-spanning region.
Gene: Immunoglobulin variable (V) gene on chromosome 14 (106,627,249 to 106,627,825, reverse strand). Ensembl gene ENSG00000224373.
Subcellular location: Secreted; Cell membrane
Pathways (Reactome):
Immune System: Antigen activates B Cell Receptor (BCR) leading to generation of second messengers; CD22 mediated BCR regulation; Classical antibody-mediated complement activation; FCERI mediated Ca+2 mobilization; FCERI mediated MAPK activation; FCERI mediated NF-kB activation; FCGR activation; Fc epsilon receptor (FCERI) signaling; Immunoregulatory interactions between a Lymphoid and a non-Lymphoid cell; Initial triggering of complement; Regulation of Complement cascade; Regulation of actin dynamics for phagocytic cup formation; Role of LAT2/NTAL/LAB on calcium mobilization; Role of phospholipids in phagocytosis
Disease: FCGR3A-mediated IL10 synthesis; FCGR3A-mediated phagocytosis; Potential therapeutics for SARS
Hemostasis: Cell surface interactions at the vascular wall
Vesicle-mediated transport: Scavenging of heme from plasma
Gene Ontology:
Molecular function: antigen binding
Biological process: immune response; immunoglobulin mediated immune response
Cellular component: extracellular region; plasma membrane
Genetic constraint (gnomAD): Missense variants: 31 observed, 25.42 expected, observed/expected ratio (o/e) 1.22, 90% interval 0.92 to 1.64. Synonymous variants: 8 observed, 7.6 expected, observed/expected ratio (o/e) 1.05, 90% interval 0.61 to 1.77.
Homologues: Paralogues in human: IGHV4-61 (99% identical), IGHV4-39 (97% identical), IGHV4-4 (93% identical), IGHV4-28 (92% identical), IGHV4-31 (92% identical), IGHV4OR15-8 (92% identical), IGHV4-34 (91% identical), IGHV6-1 (64% identical), IGHV2-26 (58% identical), IGHV2-5 (56% identical), IGHV3-11 (56% identical), IGHV2-70 (55% identical), and 65 more.